CD276 (CD276 molecule)
Diseases named in the same sentence as CD276 in open-access papers (continued):
Sharing a sentence is not in itself a finding about the gene and the disease.
tumor (continued). "Low and dispersed CD276 expression was noted in some tumor samples, while its expression was high in other tumor samples." (PMID 33845814, 2021). "The overexpression of CD276 is related to poor prognosis in tumor patients and the potential of tumor invasion and metastasis." (PMID 34354750, 2021). "Elevated expression of CD276 enhances the TLT-2-mediated CD8+ cytotoxic T-lymphocyte response to tumor in mice." (PMID 33845814, 2021). "For instance, some of the novel CD276 immunohistochemical results such as lower-level CD276 expression outside of the tumor vasculature when using the Ventana system deserve additional study." (PMID 33557152, 2021). "Each CD44+ cell-type functions immunosuppression through different ways: CD44+ tumor cells express CD276, IL13, VEGFA, and IDO1; CD44+ TAMs express IL10, TGFB1, VEGFA, and HAVCR2; CD44+ T cells express CD274, TGFB1, CTLA4, LAG3, and PDCD1." (PMID 35187044, 2021). "In pT2–T4 tumor tissue samples, CD276 was overexpressed (median score 185) when compared to corresponding healthy tissues from the same patients (median score 50; p < 0.001)." (PMID 33845814, 2021). "At the same time, CD276 is also abnormally expressed in a variety of tumors and participates in tumor proliferation, apoptosis, differentiation, invasion and interepithelial transformation." (PMID 34917619, 2021). "We also assessed the role of CD276 within the immune micro-environment, effect on tumor progression, and the potential therapeutic effect of CD276 targeted therapy for malignancies." (PMID 33842369, 2021). "Clearly, further studies are necessary to understand the connection between CD276 expression on tumor and tumor-infiltrating lymphocytes." (PMID 34290311, 2021). "On the contrary, CD276-CAR NK-92 cells show high cytotoxic potential lysing tumor spheroids from the outside, indicating that lysis of the spheroids is not dependent on complete infiltration." (PMID 33925968, 2021). "In GC with a high expression of CD276, a reduced density of CD8+ T-cells was observed in the center of the tumor, which suggests the involvement of CD276 in the mechanisms of tumor escape from the immune response." (PMID 34943606, 2021). "A previous study demonstrated that CD276, expressed in multiple tumor lines, tumor-infiltrating dendritic cells, and macrophages, can inhibit T-cell activation and autoimmunity." (PMID 35141255, 2021). "Due to increased expression levels of CD276 in multiple tumors and low expression in a variety of normal tissues, numerous studies used CD276 as the target for tumor gene therapy and monoclonal antibody therapy." (PMID 33842369, 2021). "The expression of CD276 showed a weak but statistically significant positive correlation with tumor diameter (Spearman’s rank correlation coefficient = 0.31, p = 0.028)." (PMID 34680929, 2021). "Meanwhile, a recent preclinical study has found that targeting CD276 by CAR-T cells effectively inhibited PDAC tumor growth in vitro and in vivo, suggesting the potential efficacy in a selected subgroup of PDAC patients." (PMID 35002712, 2021). "So far, different anti-CD276 blocking antibodies have been examined in pre-clinical as well as phase 1 clinical studies and have demonstrated a good safety and powerful anti-tumor profile." (PMID 33925968, 2021). "Only long-lasting hypoxic culture conditions as well as incubation with tumor cell supernatants slightly affected CD276-CAR NK-92 cell function." (PMID 33925968, 2021). "Overall, there are many intertwined factors contributing to the regulation of CD276 expression, which result in the observed relatively low level expression in normal tissue and elevated expression in tumor tissue." (PMID 33842369, 2021). "CD276 has been reported to promote tumor progression by inhibiting the functions of NK and CD8+ T cells, and its expression levels were associated with poor prognosis in multiple cancers." (PMID 35002712, 2021).
tumor (continued). "CD276-CAR NK-92 cells that were added to tumor spheroids in the presence of CXCL12 were able to migrate quickly and show high cytotoxic potential within 24 h." (PMID 33925968, 2021). "In summary, increased expression level of CD276 in tumor tissues compared to normal tissues provides the potential for CD276 CAR-T cells as a treatment for tumors." (PMID 33842369, 2021). "Expression of CD276 in ccRCC specimens is correlated with adverse clinicopathologic outcomes (tumor size, tumor stage, nuclear grading, coagulative tumor necrosis, and sarcomatoid differentiation)." (PMID 33842369, 2021). "Our data show a role for tumor-expressed CD276 on the macrophage recruitment into the tumor spheroid, and also in regulation of the extracellular matrix modulator PAI-1." (PMID 34290311, 2021). "The regulation of CD276 expression is closely related to tumor growth, invasion, metastasis, and immune escape." (PMID 33842369, 2021). "Our data suggest that tumor-expressed CD276 contributes to macrophage recruitment in spheroid, possibly by influencing extracellular matrix (ECM) remodeling." (PMID 34290311, 2021). "In another study, CD276 prevented activation of anti-tumor responses by blocking CD4+Th1- activation." (PMID 33845814, 2021). "Another important immune-checkpoint gene CD276, also known as B7-H3, has been observed to be up-regulated in the high-risk group, which is consistent with the previous evidence that CD276 is generally overexpressed in tumor tissues compared to normal tissues and could lead to worse survival." (PMID 34899849, 2021). "CD276, expressed in multiple tumor lines, tumor-infiltrating dendritic cells, and macrophages, can inhibit T-cell activation and autoimmunity (Son, Kwon & Cho, 2019)." (PMID 33850663, 2021). "CD276 is a strong immunosuppressive checkpoint that is highly expressed in numerous solid tumors, which promotes the immune escape of tumor cells from the cytotoxic effects of interferon-gamma (IFN-γ) and tumor necrosis factor-alpha (TNF-α)." (PMID 35052695, 2021). "B7 homolog 3 protein (B7-H3), also known as CD276, is a B7 superfamily molecule that is expressed in the tumor microenvironment and has coinhibitory function on immune effector cells, most prominently decreasing T cell function." (PMID 34199783, 2021). "We also noted a statistical increase of B7-H3 in MGMT methylated tumour core B7-H3 (CD276) against MGMT unmethylated tumour core (p = 0.023)." (PMID 33995529, 2021). "CD276 expression level was found to be positively correlated with Gleason score, tumor stage, castration resistance, and metastasis." (PMID 33842369, 2021). "In other studies, tumor therapy by a PD-1 inhibitor reduced the expression of CD276 on bladder cancer carcinoma cells significantly in about 67% of samples investigated." (PMID 33845814, 2021). "CD276 was found to be overexpressed in various tumor cells, which acts as an inhibitor of T cell function and indicates poor prognosis in cancer patients." (PMID 34610581, 2021). "CD276 (B7-H3) is a member of the B7 superfamily of immune checkpoints and recently emerged as an important prognostic tumor marker as well as a promising target structure for immunotherapy." (PMID 33925968, 2021). "Inhibition of CD276 is able to suppress tumor growth, and CD276-targeted therapy has also shown broad tumoricidal and antimetastatic activity in vivo." (PMID 31998416, 2020). "While comparing their expression for immunotherapy molecules we found B7-H3 (CD276); one of the B7 family checkpoint molecule to be overexpressed in RB tumor compared to the retinal tissue." (PMID 32576886, 2020). "Both tumor cell expression and vascular expression of CD276 were differentially distributed in different gender groups (P = 0.01 and P = 0.003, separately)." (PMID 31998416, 2020). "The main reason is that CD276 has a dual role in tumor cells by interacting with T-suppressor cells or T-effector cells." (PMID 32742491, 2020).
tumor (continued). "In the Kaplan–Meier analysis, ACC cases with a higher intensity of CD276 expression in tumor cells exhibited significantly poorer overall survival compared to those with lower CD276 expression levels (P = 0.007)." (PMID 31998416, 2020). "The results further indicate the importance of understanding the CD276-regulated immune response and tumor aggressive behaviors in future studies." (PMID 31998416, 2020). "Multivariate Cox regression modeling suggested that surgical assessment (R1/2/X, HR = 2.8, 95% CI: 1.23-6.39, P = 0.014) and CD276 expression in tumor cells (HR = 7.52, 95% CI: 2.47-22.91, P < 0.001) were independent recurrence risk factors for ACC." (PMID 31998416, 2020). "Our study was designed to evaluate the prevalence of tumor derived circulating endothelial cells (CD276+CEC) measured by flowcytometry in patients with mCRC and explore the predictive value for response to systemic therapy." (PMID 31948091, 2020). "CD276, PDCD1LG2 (PD-L2) were a member of the B7 transmembrane glycoprotein family, and their expression were associated with poor prognosis and tumor immune escape of NSCLC." (PMID 32699529, 2020). "PET/MRI and biodistribution analysis showed significantly higher tumor uptake compared with mice that were co-injected with an excess unlabeled tracer, indicating CD276 specificity." (PMID 31696402, 2019). "The antigen CD276 (or B7-H3), which is an immunoregulator and cell surface tumor endothelial marker, showed a higher expression in EVs from metastatic cells." (PMID 31528221, 2019). "A humanized anti-B7-H3 mAb, 89Zr-labeled 5573a, has been used in immunodeficient CD276+ MDA-MB-231 tumor-bearing mice for non-invasive imaging of CD276." (PMID 31696402, 2019). "The transmembrane glycoprotein CD276 is an immuno-regulatory molecule overexpressed on endothelial cells of tumor vasculature and in different types of tumors, while limited expression is seen in normal cells." (PMID 33568892, 2019). "The data suggested that PDT targeted to CD276 can potentially be employed to selectively kill tumor vasculature and directly or indirectly tumor cells." (PMID 33568892, 2019). "In a mouse model, a drug conjugated with anti CD276 antibody, eradicated both large established tumours and metastases and improved long-term overall survival likely because of the targeting of both angiogenic and non-angiogenic intra-tumour blood vessels." (PMID 35582580, 2019). "First, it was shown that 4T1 cells and tumor vasculature overexpress CD276, using immunofluorescence staining with an αCD276 antibody, conjugated to Fluorescein (FITC)." (PMID 33568892, 2019). "B7-H3 (also known as CD276) belongs to a family of immune modulators (known as the B7 family) that includes PD-L1 (or B7-H1), and has been associated tumor immunosuppression and decreased survival of cancer patients." (PMID 28486396, 2017). "The precise functions of CD276 in tumor immunity are complicated as both T cell co-stimulatory and co-inhibitory effects have been reported." (PMID 27329595, 2016). "Recently, emerging studies reveal that high tumor CD276 expression is correlated with more advanced disease and poor prognosis." (PMID 27329595, 2016). "And CD276 also affects tumor progression and chemosensitivity by regulating oncogenic signaling pathways activated in non-immunological systems." (PMID 27329595, 2016). "An overexpression of B7-H3 (CD276) on tumor cells has been reported in selected cancers with both stimulatory and inhibitory properties." (PMID 24734218, 2014). "Twenty-one different antibodies were used to capture and phenotype the exosomes for both the general exosomer markers, membrane markers (e.g. PLAP, HLA-ABC) and tumour-associated antigens (e.g. EpCam, HER2, CD276 [B7H3])." (PMID 26082317, 2013).
tumor (continued). "With serial analysis of gene expression, investigators compared gene expression from endothelial cells isolated from normal or malignant tissue, and found that several transcripts (e.g., CD276) were specifically elevated in the tumor endothelium." (PMID 21385454, 2011). "Specifically, we developed two-site, that is, cysteine and lysine, co-conjugation technologies to link a chemotherapeutic agent for direct tumor cell killing and a Toll-like receptor dual agonist for tumoral immunity enhancement to our humanized anti-CD276 (B7-H3) mAb." (PMID 42013359, 2026). "Tumor regions, as indicated by squares, were analysed for their percentage of CD276-positive cells." (PMID 40722088, 2025). "High expression of the CD276 (B7-H3) marker in stomach or intestine correlates with a decrease in the CD8+ T cells density within the tumor mass, suggesting that this marker may be involved in the immune response evasion of cancer cells." (PMID 40136652, 2025). "Gene set enrichment analyses (GSEA) revealed that CD276 is associated with extracellular matrix (ECM) pathways, which may indicate its role in promoting tumor progression by influencing tumor cell migration and invasion." (PMID 40135048, 2025). "The downregulation of CD276 following a reduction in AK5 expression in tumor cells suggests that targeting AK5 may enhance the efficacy of immunotherapies that leverage the CD276 checkpoint strategy." (PMID 40161494, 2025). "The dysregulation of CD276, an immune checkpoint molecule, aligns with reports suggesting its role in immune evasion and enhanced inflammatory responses in the tumor microenvironment, which may intensify CRS during CAR T-cell therapy." (PMID 40370902, 2025). "B7 homolog 3 protein (also known as CD276) is a member of the B7 family overexpressed in tumor tissues and is a costimulatory/coinhibitory immunoregulatory protein that performs a dual role in the immune system during T-cell activation and is an emerging target for antibody-based immunotherapy." (PMID 40422520, 2025). "CD276 expression in tumor vasculature may facilitate T cell infiltration into the tumor, thereby overcoming a limiting factor for successful T cell-based immunotherapy in solid cancers." (PMID 40707958, 2025). "Therapeutic targeting of CD276 may enhance immune cell infiltration into the tumor site by affecting its expression on tumor cells and tumor vasculature, which addresses a critical challenge for the successful treatment of solid tumors." (PMID 40707958, 2025). "In addition, CD276 has been shown to transduce anti-apoptotic signals in tumor cells, thereby contributing to accelerated tumor growth and tumorigenesis." (PMID 40214484, 2025). "Therefore, chimeric antigen receptor (CAR) T cells have been engineered to target FGFR4 and CD276, thereby successfully reducing T cell exhaustion, enhancing T cell persistence, and restoring a robust anti-tumor immune response." (PMID 41007114, 2025). "Lastly, we confirmed CD276-expression by IHC on a TMA containing 39 primary patient tumor samples." (PMID 40722088, 2025). "Here, we integrated and refined TCGA sourced tumor-related DEGs with genes from TISIDB related to immune to ultimately establish a four-gene prognostic signature comprising CD276, MS4A1, IGFBP1 and CD200, which has the ability to reflect ICIs responses and survival outcomes." (PMID 41488652, 2025). "Interestingly, the more pronounced T cell exhaustion and CD276 expression in WLWH resulted in aberrant spatial T cell distribution showing a regional heterogeneity within the tumor." (PMID 40393975, 2025). "For example, expression levels of PD-L1, CD276 (B7-H3), or tumor-infiltrating lymphocyte (TIL) profiles could serve as early indicators of treatment success." (PMID 41007114, 2025).
tumor (continued). "To account for additional effector functions of CAR-NK cells besides direct tumor cell killing, we tested TNFα and IFNγ secretion of CD276-directed CAR NK-92 cells after co-incubation with all target cell lines tested before in cell killing experiments (except AR6)." (PMID 40469103, 2025). "Several inhibitory markers, including CD276, HAVCR2, CTLA4, PDCD1LG2, LAIR1, and ADORA2A, were significantly upregulated in the high-risk group (p < 0.05), suggesting an immunosuppressive tumor microenvironment." (PMID 40963600, 2025). "This study utilized a tumor model induced by N-butyl-N-(4-hydroxybutyl) nitrosamine in male BC mice, and 93 tumor tissue specimens from BC patients undergoing surgical treatment were analyzed for correlations between CD276 expression and patient survival." (PMID 40177538, 2025). "Similarly, these reverse correlation phenomenon, high correlation in normal samples and low correlation in tumor samples, also performed in the expression correlation between HuR and PD-1 (CD276)." (PMID 40853971, 2025). "In the high-risk group, we observed a substantial upregulation of several immune-suppressive and regulatory molecules, including PD-L1 (CD274), CD276, TIM-3 (HAVCR2), LAG3, and TGFB1, all of which are associated with an immunosuppressive tumor microenvironment." (PMID 40959429, 2025). "From a therapeutic standpoint, co-targeting IGSF8 and CD276 may provide synergistic benefits by simultaneously enhancing T and NK cell activity and reversing tumor immune evasion." (PMID 40936932, 2025). "71.8% of primary patient tumor samples express CD276 at the highest level (+++)." (PMID 40722088, 2025). "In addition, the immunofluorescence co-staining results showed that more CD276+ tumor cells and CD16+ NK cells were existed in pre-NCT and pre-NICT group." (PMID 39076970, 2024). "An increase in CD276 expression is correlated with tumor progression and poor survival." (PMID 39766794, 2024). "CD276 is believed to be involved in regulating the T-cell-mediated immune response and may play a protective role in tumor cells by inhibiting natural-killer mediated cell lysis." (PMID 38361753, 2024). "In this study, we demonstrated that ZDHHC4/12/18/24 and APT2 may affect CD276 palmitoylation and, therefore, tumor growth." (PMID 38177255, 2024). "We evaluated the anti-tumor efficacy of CD276 CAR-T and further compared the functional assessment of Dash CAR-T and conventional CAR-T in vitro and in vivo by detecting the immunophenotypes, killing ability, expansion capacity and tumor-eradicating effect of CAR-T." (PMID 38978106, 2024). "Furthermore, related studies have reported that an increase in CD276 expression is correlated with tumor progression, and we confirmed this in ACC, BLCA, LIHC, LUAD, THCA, and OV." (PMID 39766794, 2024). "Various tumor cells, vascular endothelial cells within tumors, and immune infiltrates such as dendritic cells and macrophages exhibit widespread and aberrant expression of the inhibitory molecule CD276." (PMID 39319055, 2024). "Additionally, there is a potential for “on-target, off-tumor” toxicity with bsAbs, given the limited expression of CD276 on endothelial cells." (PMID 38637557, 2024). "To examined whether activated T cells play a role in the anti-tumor effects of CD276 cKO, we block T lymphocytes following MB49 subcutaneous implantation by injection of anti-CD4 or anti-CD8 antibodies." (PMID 38561369, 2024). "Furthermore, the proportion of T-cells transduced with FGFR4.28HTM.28z-CD276.8HTM.BBz BiCisCAR that expressed exhaustion markers was significantly lower within tumor (CD39 and Tim-3) and in the blood (CD39 and LAG-3) compared to those observed with other CARs." (PMID 39043633, 2024). "In our in vivo experiments, Plek2 knockdown was associated with decreased expression of Cd276 (B7-H3), suggesting that PLEK2 might foster an immunosuppressive tumor microenvironment (TME)." (PMID 39546161, 2024).